STAT1 (signal transducer and activator of transcription 1)
Diseases named in the same sentence as STAT1 in open-access papers (continued):
Sharing a sentence is not in itself a finding about the gene and the disease.
meningioma (3 papers, 2020 to 2022). A generally slow growing tumor attached to the dura mater. "Taken together, our results demonstrate that STAT1 overexpression is associated with an increased proliferation of meningioma tumor cells." (PMID 32642677, 2020). "Our findings underline a crucial role of the EGFR and STAT1 signaling in the pathology of meningiomas and point to a therapeutic potential of its inhibition." (PMID 32642677, 2020). "The pharmaceutical inhibition of EGFR in meningioma caused the deactivation of STAT1 and other cancer-related pathways, eventually leading to a significant reduction in cellular proliferation." (PMID 32642677, 2020). "Our experiments showed that the PP2A inhibitor LB-100 can significantly increase the phosphorylation of STAT1 and the expression of B7-H3 in malignant meningiomas at the cellular level." (PMID 36203966, 2022). "We analyzed STAT1 overexpression and phosphorylation in 131 meningiomas of different grades and locations by utilizing several techniques, including Western blots, qPCR, and immunocytochemistry." (PMID 32642677, 2020). "In the present study, we identified STAT1 as overexpressed and phosphorylated in meningioma compared to normal and we show that its overexpression correlates with an increased proliferation of the tumor cells as well as activation of AKT and ERK1/2." (PMID 32642677, 2020). "Overall, we examined 131 meningiomas versus 10 normal meninges and 5 normal brains and we demonstrate substantial overexpression of STAT1 in 100 of them with a variety of methods." (PMID 32642677, 2020). "Since STAT1 is constitutively phosphorylated in meningioma, we used U251-MG cells as a model because this cell line showed levels of total and pSTAT1 lower than HMC." (PMID 32642677, 2020). "Then, we examined STAT1 expression and phosphorylation in meningioma-derived primary cells (MN) and BM-125 compared to HMC." (PMID 32642677, 2020). "In conclusion, we provide clear evidence of STAT1 overexpression in meningioma of different genotype and its correlation with increased cellular proliferation." (PMID 32642677, 2020). "To investigate the biological significance of STAT1 overexpression in meningioma we silenced the protein in MN cells." (PMID 32642677, 2020). "Immunohistochemical studies validated STAT1 overexpression in all meningioma samples; also pSTAT1-Y701 and -S727 showed higher staining compared to normal meninges and an increasing score throughout the grades." (PMID 32642677, 2020). "The PP2A inhibitor LB-100 increased the phosphorylation of STAT1 and B7-H3 expression, which could increase the sensitivity of malignant meningiomas to B7-H3 targeted immunotherapy." (PMID 36203966, 2022). "Notably, the PP2A inhibitor LB-100 increased the phosphorylation of STAT1, thereby increasing the expression of the immune checkpoint protein B7-H3 in malignant meningioma cells in vitro." (PMID 36203966, 2022). "We also aimed to determine whether NAMPT regulates the immune checkpoint in anaplastic meningiomas by regulating STAT1." (PMID 35515130, 2022). "Supporting with the initial identification of STAT1 in meningioma—K.B." (PMID 32642677, 2020). "Hence, we showed that EGFR is responsible for STAT1 overexpression and constitutive activation in meningioma, which consequently increases the proliferation of the tumor cells." (PMID 32642677, 2020). "We identified STAT1 as overexpressed and activated in 84% of meningioma examined." (PMID 32642677, 2020). "We analyzed STAT1 expression in meningioma tumors compared to normal meninges (NMT)." (PMID 32642677, 2020). "Therefore, we hypothesized other mechanisms must be involved in maintaining STAT1 in a constitutive phosphorylated form in the meningioma samples analyzed." (PMID 32642677, 2020). "STAT1 and CD276 were highly expressed in malignant meningiomas compared with meningothelial meningiomas." (PMID 36203966, 2022).
meningioma (continued). "STAT1 is known to be activated by EGFR, so we investigated the tyrosine kinase and found that EGFR was also constitutively phosphorylated in meningioma and was responsible for the aberrant phosphorylation of STAT1." (PMID 32642677, 2020). "These experiments confirmed that the constitutive phosphorylation of STAT1 on both phosphosites affects the activation of the AKT and ERK1/2 pathways as well as the proliferation of the cells in agreement with STAT1 knockdown results in meningioma." (PMID 32642677, 2020). "STAT1 was found widely overexpressed in meningioma but not in the corresponding healthy controls." (PMID 32642677, 2020). "However, there is no report on the expression of STAT1 and B7-H3 in meningioma." (PMID 36203966, 2022).
non-alcoholic steatohepatitis (3 papers, 2022). "STAT1 and STAT2 have been shown to inhibit HCV replication after being activated by IFNs, while activation of STAT1 and STAT3 are found in non-alcoholic steatohepatitis (NASH)." (PMID 35871161, 2022). "In a mouse model of non-alcoholic steatohepatitis, inhibition of BET proteins significantly reduces the expression of STAT1-dependent IFN-γ in liver tissue." (PMID 35619690, 2022).
pulmonary TB (3 papers, 2020 to 2023). "Our study identified unique gene signatures (IL-27, STAT1, IRF1, TLR4, IL-15, IL-2RA, IL-24, TGFβ, CD28, CD80, NFATC1, and PTGDR2) that discriminate active pulmonary TB from uninfected controls using unstimulated PBMCs." (PMID 37460564, 2023). "STAT1 has also been identified as a key gene and a potential biomarker in TB65–67, and our results also support this finding in pulmonary TB." (PMID 37460564, 2023).
scleroderma (3 papers, 2008 to 2019). Scleroderma is a rare autoimmune connective tissue disorder characterized by abnormal hardening of the skin and, sometimes, other organs. "The other indispensable formula target STAT1 has been demonstrated to be blocked in the fibroblasts from scleroderma-associated interstitial lung disease." (PMID 30674993, 2019). "In one case study, several high-scoring predicted targets for scleroderma formed a subnetwork consisting of IFN and TLR signaling pathways and centered around the transcription factor STAT1." (PMID 23593264, 2013). "STAT1 phosphorylation was present in cellular nuclei in 7 of 10 scleroderma biopsies, but negative in all 7 normal controls tested (p = 0.006)." (PMID 18197262, 2008).
small cell lung carcinoma (3 papers, 2023 to 2024). Small cell lung cancer (SCLC) is a highly aggressive malignant neoplasm, accounting for 10-15% of lung cancer cases, characterized byrapid growth, and early metastasis. "Small cell lung carcinoma (SCLC) cell lines expressing higher levels of STAT1 are more resistant to DOX, the chemotherapy agent etoposide (Etoposide), and radiotherapy." (PMID 39405604, 2024).
soft tissue sarcoma (3 papers, 2014 to 2022). A malignant neoplasm arising from muscle tissue, adipose tissue, blood vessels, fibrous tissue, or other supportive tissues excluding the bones. "A similar distinct association of STAT1 and pY-STAT1 levels with patient’s survival has been recently reported for soft tissue sarcomas." (PMID 24725474, 2014). "In soft tissue sarcoma, high levels of STAT1 in tumor cells correlated with poor prognosis and metastasis." (PMID 32275681, 2020).
T-cell lymphoma (3 papers, 2015 to 2025). "In addition, IL31 is highly expressed in hematological malignancies such as follicular lymphoma, germinal cancer derived B-cell malignancy, and T cell lymphoma, and was found to contribute to tumor growth via the STAT1/STAT3 signaling pathway." (PMID 28147314, 2017).
Thrombosis (3 papers, 2021 to 2025). "Metabolic memory sustained byO-GlcNAc/CaMKIIδ/STAT1/miR-15-16 loops in endothelial sEVs.Gut-heart axis disruption via TMAO (thrombosis/endothelial injury) and diminishedSCFAs." (PMID 41209114, 2025). "However, inactivation of STAT1 by such approaches may make individuals more prone to infection because of drastic effects on the inflammatory response, as has been shown recently in the case of inhibition of IL‐1β in The Canakinumab Anti‐inflammatory Thrombosis Outcome Study." (PMID 34569651, 2021).
thyroiditis (3 papers, 2016 to 2021). Inflammation of the thyroid gland. "The high prevalence of thyroiditis which we observed in the STAT1 mutated CMC patients in this study is an interesting aspect." (PMID 26604104, 2016). "Finally, gain-of-function (GOF) missense mutations in the signal transducer and activator of transcription 1 (STAT1) were shown to cause autosomal dominant familial CMC, often associated with thyroid disease, and represent the most common genetic etiology of CMC." (PMID 26604104, 2016).
visceral leishmaniasis (3 papers, 2021 to 2023). A severe form of leishmaniasis characterized by irregular bouts of fever, substantial weight loss, swelling of the spleen and liver, and anemia (which may be serious). "Interestingly, a similar phenomenon was observed in visceral leishmaniasis, where a lack of STAT1 inhibited the recruitment of monocytes and the hosts were relatively more resistant to L. donovani infection." (PMID 34684235, 2021).
acute GVHD (2 papers, 2021 to 2023). "The absence of IFN-γ receptor (IFN-γR) or STAT1 signaling in donor cells has been shown to result in reduced induction of acute graft-versus-host disease (GVHD)." (PMID 36445781, 2023). "Absence of the IFN-γR/STAT1 signaling in recipient mice leads to increased acute GVHD." (PMID 36445781, 2023). "This asserts that the anti-inflammatory effects of BRD4 inhibition are independent of STAT1, which is a target of the currently FDA approved Jak1/2 inhibitor, ruxolitinib, for steroid refractory acute GVHD." (PMID 34722316, 2021).
Acute hepatitis (2 papers, 2017). Acute hepatic injury resulting from inflammation typically accompanied by increased serum alanine transaminase activity. "In the current study, Sophocarpine pretreatment significantly inhibited STAT1 activity and increased the expression of SOCS1, subsequently downregulating its signaling proteins T-bet and inhibiting the production of Th1 cytokines, which protects mice from ConA-induced acute hepatitis." (PMID 28377718, 2017).
acute leukemia (2 papers, 2019 to 2021). A clonal (malignant) hematopoietic disorder with an acute onset, affecting the bone marrow and the peripheral blood. "Activation of STAT1 is important in ATRA and other various drug-induced differentiation therapies for myeloid cells in APL and other subtypes of acute leukemia." (PMID 31117333, 2019).
acute respiratory failure (2 papers, 2020 to 2021). Life-threatening respiratory failure that develops rapidly. "Our study assessed neutrophil activation, the differential expression of ISGs and activation of the STAT1 signaling pathway, and NETosis in the airways of intubated children with acute respiratory failure due to lower respiratory tract infections." (PMID 33149247, 2020).
age-related macular degeneration (2 papers, 2019 to 2022). Age-related loss of vision in the central portion of the retina (macula), secondary to retinal degeneration. "In another study, treatment of retinal pigment epithelium (RPE) cells with amyloid-β1-40, a known inflammatory trigger in Age-related macular degeneration (AMD) caused a significant induction of inflammatory genes such as BST2, STAT1, RSAD2, MX2, OAS1&2, IFNL44 and LXN43." (PMID 30914656, 2019). "STAT1 and NF-κB may work together as a complex to control the upregulation in LCN2 expression in the retina and stimulate an inflammatory response, leading to increased infiltration of LCN2-positive neutrophils in the choroid and retina of early age-related macular degeneration." (PMID 36555403, 2022).
alopecia (2 papers, 2024). Hair loss usually from the scalp. "The signal pathways associated with IL2-Rβ, JAK1, and STAT1 in CD8+ T cells are involved in alopecia." (PMID 39063064, 2024). "First, in the genetic modulation of HFDPSCs, two materials modulated alopecia-associated genes, including genes for TCF, β-catenin, Wnt, STAT1, 5α-reductase type 1, IL-15R, and NKG2DL." (PMID 39063064, 2024). "In CD8+ T cells, GE2000 and E40 downregulated alopecia-activating markers including IL2-Rβ, JAK1 (Janus kinase 1), and STAT1 (signal transducer and activator of transcription 1) under DT1 influence." (PMID 39063064, 2024). "Upon exposure to dihydrotestosterone (DT), both biomaterials upregulated genes preventing alopecia (Wnt, β-catenin, and TCF) in HFDPSCs and suppressed genes activating alopecia (STAT1, 5α-reductase type 1, IL-15R)." (PMID 39063064, 2024). "Notably, the expression of STAT1, IL-15R, and NKG2DL in epithelial cells activates alopecia through communication with CD8+ T cells." (PMID 39063064, 2024). "Additionally, expressive suppression of STAT1, 5α-reductase type 1, IL-15R, and NKG2DL molecules in follicular epithelial cells is crucial to prevent alopecia." (PMID 39063064, 2024). "Using hair follicle-specific JAK1/2 and STAT1 knockout mice, we expanded the spectrum of activity of the JAK inhibitors to HFSC-specific protection from chronic inflammation resulting in scarring alopecia." (PMID 39521937, 2024). "Additionally, they suppressed alopecia-related genes (NKG2DL, IL2-Rβ, JAK1, STAT1) in CD8+ T cells." (PMID 39063064, 2024).
aristolochic acid nephropathy (2 papers, 2021 to 2022). "Renoprotective effect of Stat1 deletion was shown in a murine model of aristolochic acid nephropathy." (PMID 35765703, 2022). "IL-6-induced STAT3 activation was observed in mice with HgCl2-induced AKI, and IFN-γ has been shown to activate STAT1 in glomerular mesangial cells in an aristolochic acid nephropathy mouse model." (PMID 33511217, 2021).
autoimmune encephalitis (2 papers, 2021). Inflammation of the brain secondary to an immune response triggered by the body itself. "P27 with biallelic STAT1 loss-of-function had glial fibrillary acidic protein (GFAP) autoimmune encephalitis." (PMID 35003119, 2021). "For Blimp-1+ eTregs in the CNS of experimental autoimmune encephalitis-diseased animals it was elucidated that Blimp-1, here maintained by proinflammatory STAT-1 signaling, ensures Foxp3 expression by inhibition of the methyltransferase Dnmt3a." (PMID 35069572, 2021).
autoimmune uveitis (2 papers, 2020 to 2021). An autoimmune form of uveitis (disease). "It has been recently reported that MSCs suppressed DCs maturation via regulating the phosphorylation of Stat1 and Stat6 in experimental autoimmune uveitis." (PMID 32283569, 2020).
bacterial Sepsis (2 papers, 2025). "FluA triggers a rapid activation of the innate immune pathways, such as NF-κB and STAT1/3, leading to an early and intense surge in proinflammatory cytokines, including TNF-α, IL-6, and IL-1β, that surpasses both the speed and magnitude of responses observed in bacterial sepsis." (PMID 41321454, 2025).
biliary tract cancer (2 papers, 2019 to 2021). "Although we were not able to show direct effects of miR-145-5p on PTPRF or PTPRS, our results suggest an important functional role of miR-145-5p in biliary tract cancer and clearly demonstrate the activation of STAT1 signaling by miR-145-4p." (PMID 30886199, 2019). "In contrast, STAT1 was neither upregulated nor phosphorylated in HCC cells suggesting that this signaling mechanism present in biliary tract cancer cells displays cell type-specificity." (PMID 30886199, 2019).
bladder urothelial carcinoma (2 papers, 2020 to 2023). "Also, the expression of NFATC1 and STAT1 are associated with PD-L1 in bladder urothelial carcinoma." (PMID 32420368, 2020).
bone cancer (2 papers, 2022 to 2023). A primary or metastatic malignant neoplasm affecting the bone or articular cartilage. "The phosphorylation ERK/STAT1 signaling pathway in spinal microglia contributes to bone cancer pain." (PMID 38041074, 2023).
bone marrow failure (2 papers, 2023 to 2025). "The case has been previously reported, and it represents one of few reports of a STAT1 mutation associated with bone marrow failure." (PMID 39873967, 2025).
brain cancer (2 papers, 2010 to 2016). A primary or metastatic malignant neoplasm affecting the brain. "We further show that STAT1 is a direct functional target of miR203, and miR203 level is negatively correlated with STAT1 expression in brain cancer patients." (PMID 27705947, 2016). "High STAT1 expression significantly correlated with poor survival in brain cancer patients." (PMID 27705947, 2016).
brain injury (2 papers, 2024). Acute and chronic (see also brain INJURIES, CHRONIC) injuries to the brain, including the cerebral hemispheres, CEREBELLUM, and brain STEM. "Furthermore, transcription factor Stat1 was shown to be driving the inflammatory process and subsequent neurological dysfunction upon traumatic brain injury (TBI)." (PMID 38607069, 2024). "Furthermore, STAT1 has been suggested to be a key mediator of the proinflammatory response of resident microglia and infiltrating blood-borne macrophages in traumatic brain injury." (PMID 39590789, 2024).
brain tumors (2 papers, 2024 to 2026). "have demonstrated that FGL2 inhibits the differentiation of CD103+ dendritic cells (DCs) induced by granulocyte‐macrophage colony‐stimulating factor (GM‐CSF) by suppressing NF‐κB, STAT1/5 and p38 activation, consequently promoting the progression of brain tumours." (PMID 39400959, 2024).
cardiomyopathy (2 papers, 2021 to 2024). A disease of the heart muscle or myocardium proper. "In response to IL-27, gene expression of TBX21, EOMES, and CXCL9, which are activated downstream of STAT1, STAT3, and STAT5 phosphorylation, was lower in patients with cardiomyopathy (i.e., the G1 and G2 groups) than that in uninfected subjects." (PMID 34061845, 2021).
carotid atherosclerosis (2 papers, 2014 to 2018). A thickening and loss of elasticity of the walls of carotid arteries that occur with formation of atherosclerotic plaques. "Combining noninvasive plaque imaging by MRI T2 mapping with Immuno-LCM gene expression profiling further identified unique activation of IFN/STAT1 pathways in carotid atherosclerosis, which correlated with the volume of plaque lipid." (PMID 30354237, 2018).
Chlamydia infection (2 papers, 2022 to 2024). "Previous studies have demonstrated that expression of STAT1 is induced following Chlamydia infection." (PMID 39194253, 2024). "Treatment with IFN-γ led to the phosphorylation of STAT1 at serine 727 and tyrosine 701 and prevented the induction of c-Myc protein and mRNA expression upon Chlamydia infection." (PMID 36155135, 2022). "In the case of Chlamydia infection of cultured cells, STAT1 translocation to the nucleus, a critical point of regulation, was reported to be reduced via an unknown mechanism." (PMID 39194253, 2024). "However, during Chlamydia infection in vitro, addition of IFNγ does not fully induce nuclear localization of its transcription factor STAT1 and expression of its target gene, IDO1." (PMID 39194253, 2024).
Chronic colitis (2 papers, 2021 to 2023). A chronic inflammatory disease of the large intestine (colon, cecum and rectum). "STAT1 inhibitor treatment also inhibited chronic colitis in mice." (PMID 37211384, 2023). "By performing ChIP-PCR experiments, we found that the recruitment of p-STAT1 to the enhancers in the LCP2 and TNFAIP2 promoters was significantly increased in tissues of mice with chronic colitis compared to mice in the control group." (PMID 34112215, 2021). "In the current study, the binding of p-STAT1 to the enhancers of TNFAIP2 and LCP2 was significantly increased in tissues from mice with chronic colitis, suggesting that both p-STAT1 deposition and H3K27ac enrichment occur on the same enhancer of both the TNFAIP2 and LCP2 genes." (PMID 34112215, 2021).